ALK (ALK receptor tyrosine kinase)
Diseases named in the same sentence as ALK in open-access papers (continued):
Sharing a sentence is not in itself a finding about the gene and the disease.
adenocarcinoma (continued). "The patients most likely to harbor ALK rearrangement were young, never or light smokers with poorly differentiated adenocarcinoma, especially with signet ring cell features, comparing with EGFR mutation or wild type cohort." (PMID 24404167, 2014). "A recent meta-analysis by Li and colleagues in 14 articles involving 125 ALK rearranged cases from 2580 NSCLC patients indicated high rate of ALK rearrangements in never-smokers with adenocarcinomas." (PMID 24959902, 2014). "Epidemiologic studies showed that ALK rearrangements tended to occur in younger patients, never or light smokers and patients with adenocarcinoma rather than squamous cell or large cell carcinoma." (PMID 24959902, 2014). "ALK rearrangement was observed predominantly in young patients, never or light smokers, and adenocarcinomas, especially with signet ring cell features and poor differentiation." (PMID 24404167, 2014). "These have recently been described in never smokers with adenocarcinoma that is ALK and EGFR wild type." (PMID 25505733, 2014). "It is well known that ALK-positive adenocarcinoma is likely to present a signet-ring cell or cribriform pattern and abundant mucin production on histological analysis: ALK-positive lesions are observed as a solid, rather than a GGO, nodule." (PMID 24885886, 2014). "Some younger, non-smokers with adenocarcinomas are found to have an ALK/EML4 fusion oncogene which is currently a target for the drug Crizotinib." (PMID 24760004, 2014). "ALK-positivity rates in the present study, 2.8% in the whole population and 5.1% in the group of EGFR and KRAS mutation-negative adenocarcinomas are consistent with those obtained in the many previous studies." (PMID 23936355, 2013). "No specific morphological characteristic for ALK-positive adenocarcinomas was identified in our cases." (PMID 23936355, 2013). "All ALK positive patients had a non squamous histology, 5 of 7 patients were adenocarcinoma and the other 2 patients had a Not Otherwise Specified (NOS) NSCLC." (PMID 23359795, 2013). "Even when an enriched population of NSCLC patients are selected on the basis of their predictive clinical characteristics, such as younger age, non-smoking status, and adenocarcinoma histology, it is difficult to identify the subsets of ALK-positive tumors." (PMID 23741400, 2013). "ALK positive patients show predominantly an adenocarcinoma histology, never/light smoking history and younger age at diagnosis." (PMID 23359795, 2013). "Most patients with ALK rearrangements typically have adenocarcinomas and are younger patients with minimal to no smoking history." (PMID 23198868, 2012). "Approximately 56% of ALK rearrangements in NSCLC occur in never smokers with adenocarcinoma histology." (PMID 22374459, 2012). "The fusions occurred predominantly in adenocarcinomas from never smokers and were mutually exclusive of mutations in EGFR, KRAS, and ALK." (PMID 22928112, 2012). "Similarly, ALK-rearranged (most commonly EML4-ALK) adenocarcinomas have been shown, albeit primarily in case reports and small series, to undergo transformation to SCLC or large-cell neuroendocrine carcinoma (LCNEC) after ALK-TKI treatment." (PMID 41516316, 2025). "Additionally, ALK fusion has been clinically observed in younger patients with adenocarcinoma with no or infrequent history of smoking; the most common type of fusion reported is EML4-ALK." (PMID 39513892, 2024). "The impact of chemotherapy on ALK+ NSCLC is modest, even though this disease seems to be more sensitive to pemetrexed-based regimens with respect to ALK- NSCLC, maybe due to the fact that ALK+ adenocarcinoma has the lowest levels of thymidylate synthase." (PMID 37232842, 2023). "Therefore, this ALK+ LCNEC patient demonstrates the adverse impact of LCNEC histology and how this can interact with molecular properties to shape an intermediate OS of 37 mo versus >5 yr in median for ALK+ adenocarcinomas, and 12 mo in median for other LCNEC." (PMID 36207130, 2022).
adenocarcinoma (continued). "Hence, 213 patients (21.3%) and 188 patients (18.8%) were categorized as EGFR/ALK-wild type adenocarcinoma and non-adenocarcinoma groups, respectively." (PMID 35980949, 2022). "Adenocarcinoma (ADC), never-smoker status, and negative CA 125 and SCC results were predictors of EGFR mutations, while younger age and never-smoker status were independent predictors of ALK rearrangement." (PMID 35624472, 2022). "False‐positive ALK‐IHC results are possible in nonadenocarcinomas, although not in adenocarcinomas." (PMID 32578376, 2020). "In the adenocarcinoma subgroup, PD-L1 expression on tumors was higher in males and smokers, and in patients with high histologic grade, with relatively high TNM status, with advanced American Joint Commission on Cancer stage, and positive for ALK rearrangement." (PMID 32749860, 2020). "EGFR/ALK-negative/unknown patients, especially for those with adenocarcinoma, can significantly benefit from chemotherapy consisting of pemetrexed plus platinum." (PMID 33163410, 2020). "However, typical biomarkers for adenocarcinoma, such as EGFR mutations and ALK abnormalities, were not adequately examined because of the old times of some enrolled patients." (PMID 33183251, 2020). "According to the literature, ALK gene rearrangement is found in 2–5% of all non-small cell lung cancers, being more common in lifetime non-smokers with adenocarcinoma as compared to smokers with adenocarcinoma, or squamous cell carcinoma." (PMID 30744199, 2019). "A 72-year-old Japanese male presented with an abnormal chest opacity that was determined to be adenocarcinoma of the left upper lobe at cT2aN1M1b Stage IV, without epidermal growth factor receptor (EGFR) mutation and anaplastic lymphoma kinase (ALK) translocation." (PMID 29554874, 2018). "Prior to 2016, effective second-line treatment options in non-small cell lung cancer (NSCLC), particularly in patients with adenocarcinoma who are not eligible for epidermal growth factor receptor (EGFR)- or anaplastic lymphoma kinase (ALK)-targeted therapy, were limited." (PMID 30073583, 2018). "Moreover, unlike adenocarcinomas, lung SCCs rarely harbor EGFR and ALK mutations, thus, until very recently, there has not been significant improvement in their treatment." (PMID 28653990, 2017). "In summary, our real‐world study showed that patients harboring EML4‐ALK rearrangement tended to be younger at diagnosis, and more of them were nonsmokers and pathological diagnosed with adenocarcinoma compared with those without ALK rearrangement and EGFR mutation." (PMID 28374971, 2017). "In adenocarcinoma, this analysis suggested that 10.6% (50.3% if including KRAS) of cases could be eligible for emerging targeted treatments, beyond the 15.3% of cases eligible for standard EGFR or ALK targeted therapy." (PMID 28415793, 2017). "In adenocarcinoma, 10.6% of patients (50.3% if including KRAS) could potentially be eligible for emerging therapeutics, in addition to the 15.3% of patients eligible for standard EGFR or ALK inhibitors." (PMID 28415793, 2017). "Moreover, in this study, ALK-rearranged adenocarcinoma showed no lepidic growth pattern, which was prevalent in several prior studies." (PMID 27142166, 2016). "Pericardial biopsy revealed adenocarcinoma of lung primary, immunohistochemistry (IHC) and molecular testing for epidermal growth factor receptor (EGFR) mutation and anaplastic lymphoma kinase (ALK) rearrangement were negative." (PMID 26237019, 2014). "Because there was no false-negative ALK IHC results using the D5F3 antibody in 368 adenocarcinomas, ALK IHC could be a suitable screening method for ALK rearrangement." (PMID 24667320, 2014). "ALK positive patients were predominantly never smokers (71.4%) and adenocarcinoma (71.4%)." (PMID 23359795, 2013). "Additionally, none of the 110 IHC-negative cases with adenocarcinoma histology showed ALK rearrangements by FISH." (PMID 23741400, 2013).
adenocarcinoma (continued). "Majority of ALK rearrangements were identified in adenocarcinoma and non-smokers." (PMID 23951022, 2013). "However, we found no specific morphological characteristic for ALK-positive adenocarcinomas, and most were histologically heterogeneous, i.e. a mixture of various growth patterns." (PMID 23936355, 2013). "The diagnosis of adenocarcinoma (epidermal growth factor receptor (EGFR) mutation exon 19 deletion, programmed death ligand 1 (PD-L1) <1%, c-ros oncogene (ROS1) negative, anaplastic lymphoma kinase (ALK) negative) was established through pleural fluid cytology and bronchoscopy." (PMID 39479150, 2024). "In addition, it was 2.3% among 129 adenocarcinomas without EGFR/ALK aberrations." (PMID 37374289, 2023). "The different frequency of EGFR and ALK subtypes between TTF-1 positive and TTF-1 negative subtypes might be linked to the fact that TTF-1 negative tumors in biopsies represent a group enriched in rare adenocarcinomas subtypes." (PMID 35885495, 2022). "Among those, the rearrangement between the Anaplastic lymphoma kinase (ALK) and the echinoderm microtubule-associated protein-like 4 (EML4) is identified in 3–7% of NSCLC cases, most commonly in younger patients, non-smokers, and those with adenocarcinoma histology." (PMID 34885137, 2021). "Notably, the frequency of ALK fusions in patients with adenocarcinomas that did not exhibit EGFR/KRAS mutations reached 45.0% (9/21), strongly indicating that only a specific molecular subset of adenocarcinomas is characterized by EML4-ALK fusion." (PMID 20624322, 2010). "Among these, the rearrangements in the anaplastic lymphoma kinase (ALK) gene account for 3-7% of NSCLC and are more frequently observed in young female, never or light-smoking patients, and with adenocarcinoma histology." (PMID 41357598, 2025). "Histopathological and immunohistochemical examinations revealed poorly differentiated adenocarcinoma and PDL 1, ALK and EGFR tests were negative." (PMID 40429388, 2025). "Given the therapeutic relevance of ALK fusions, inclusion of ALK immunohistochemistry in any atypical-looking or androgen receptor poor SDC and high-grade adenocarcinoma, not otherwise specified is recommended." (PMID 38217715, 2024). "Rearrangement of the anaplastic lymphoma kinase (ALK) gene is observed in 2%–7% of NSCLC patients, and is particularly frequent in younger individuals, non-smokers, and those with adenocarcinoma." (PMID 39555099, 2024). "ALK, ROS1, and RET rearrangement is typically more common among younger individuals, non-smokers, and light smokers who have been diagnosed with adenocarcinoma." (PMID 39685930, 2024). "Patients with ALK-positive NSCLC have unique clinical and pathologic characteristics including young age, never or light smoking history, adenocarcinoma histology, and the presence of signet-ring cells, etc.." (PMID 31696059, 2019). "Similar to ALK-rearranged adenocarcinomas, an intracellular mucin vacuole is frequently observed in ROS1-rearranged adenocarcinomas; therefore, inadequate immunostaining should not be missed." (PMID 29538329, 2018). "ROS1 rearrangements are more commonly found in never or mild smokers patients with adenocarcinoma (ADC) histology and in triple negative (EGFR/KRAS/ALK) population, similar to patients with ALK-rearranged NSCLC." (PMID 26783962, 2016). "Similar to the clinical features of ALK-rearranged NSCLC, ROS1 rearrangement are more likely to be found in younger, never smokers with histologic diagnosis of adenocarcinoma, with an occurrence rate ranging from 1 to 2%." (PMID 26187152, 2015). "ALK rearrangements occur in approximately 3–5% of NSCLC patients, more common in patients with adenocarcinoma, younger patients, and never or light smokers as well as generally mutually exclusive with other identified oncogenic drivers." (PMID 26187152, 2015).
adenocarcinoma (continued). "EML4/ALK rearrangements are detected in approximately 4–5% of patients with NSCLC, mostly in young patients with adenocarcinoma who are non-smokers or light smokers." (PMID 26134262, 2015). "The product of EML4-ALK fusion is a chimeric protein with constitutive ALK activity and is detected in 3–6% of unselected NSCLC and especially among never-smokers or light ex-smokers who have adenocarcinoma histology." (PMID 25157335, 2014). "On the other hand, among 473 NSCLC cases, we randomly selected 110 IHC-neagative cases with adenocarcinoma histology to evaluate ALK rearrangement by FISH, and found that there were no cases in which ALK gene rearrangement was detected." (PMID 23741400, 2013). "In unselected patients with NSCLC the prevalence of ALK positivity range from 1% to 7%, but more than 30% in patients selected for EGFR Wild-Type (WT), adenocarcinoma and no smoking history." (PMID 23359795, 2013). "EGFR, ALK, and ROS1 alterations are common for young female non-smokers with adenocarcinoma." (PMID 38605928, 2024). "In addition, adenocarcinoma showing micropapillary component, especially without EGFR/ALK aberration, should be first considered for BRAF testing, including immunohistochemistry." (PMID 37374289, 2023). "In a case report, a 76-year-old male with stage IV adenocarcinoma (cT2bN2M1b) without targetable genomic alterations, such as epidermal growth factor receptor (EGFR), anaplastic lymphoma kinase (ALK), rearranged c-ros oncogene 1 (ROS1), was diagnosed by right abdominal muscle surgical resection." (PMID 34956221, 2021). "However, among the adenocarcinoma subtype, neither EGFR nor ALK alteration impacts the outcome of this combination." (PMID 33996532, 2021). "The anaplastic lymphoma kinase (ALK) fusion gene is a rare driver aberration that occurs only in 2% to 7% of all non-small cell lung cancer (NSCLC) cases, with a predilection in never- or light-smokers and in patients with adenocarcinoma histology." (PMID 33171712, 2020). "Seventeen studies aimed at predicting EGFR status, one aimed at predicting ALK status, three at predicting both EGFR and KRAS status, one at identifying ALK/ROS1/RET fusion-positive versus fusion-negative adenocarcinomas and two at predicting the PD-L1 expression level." (PMID 32486314, 2020). "New treatments, mainly including bevacizumab, anaplastic lymphoma kinase (ALK) inhibitors, and EGFR tyrosine kinase inhibitors, have significantly improved the overall survival of patients with adenocarcinoma, but the therapeutic effects are not effective for lung SCC patients." (PMID 33111744, 2020). "Our study suggested that solid-predominant tumors had the highest expression of Mean/MWV among the various histologic subtypes, but the number of genomic triple negative adenocarcinoma was not significantly higher than that of adenocarcinoma harboring exclusive gene of either EGFR, KRAS, or ALK." (PMID 29535840, 2018). "ALK gene rearrangements are found in 2–7% of all NSCLC patients and are more likely to be found in younger patients (<50 years old) and light/never smokers and have an adenocarcinoma histology, predominantly the signet ring cell subtype." (PMID 29312572, 2017). "Clinical characteristics of NSCLC patients with ROS-1 rearrangements are similar to patients with ALK-rearranged NSCLC – more commonly seen in patients of Asian ethnicity, young age (median age 49.8 years), female sex, never-smokers, and adenocarcinoma histology." (PMID 25157335, 2014). "The history of the treatment of advanced NSCLC in ALK fusion-positive patients started in 2007 with Soda and his group’s discovery of the presence of the fusion protein ALK-EMLA4 in patients affected by NSCLC adenocarcinoma, who were mostly young patients and those who have never smoked." (PMID 39796163, 2025).
adenocarcinoma (continued). "Our patient sample had similar features to other ALK+ NSCLC populations included in several real-world studies: half the patients were female, with a mean age below 60 years, most were non-smokers, and they presented stage IV disease and adenocarcinoma histology." (PMID 35720977, 2022). "Biopsy of the right supraclavicular lymph node revealed lung tissue adenocarcinoma and negative Kirsten rat sarcoma viral oncogene homolog (K-Ras), epidermal growth factor receptor (EGFR), B-raf proto-oncogene (BRAF), C-ros oncogene 1 (ROS1), and anaplastic lymphoma kinase (ALK) rearrangement." (PMID 33728131, 2021). "Subsequently, other gene fusion partners to ALK were identified; EML4 is the most common of these, and ALK-rearrangements are found in 4–7% of non-small cell lung cancer (NSCLC) patients, mostly in younger patients with light or nonsmoking history and adenocarcinoma histology." (PMID 32640547, 2020). "The frequency of ALK rearrangement ranges from 3% to 7% in unselected NSCLC patients, which could reach to 13% ∼ 18%, if the patient population is selected according to specific clinicopathologic characteristics, especially in young, never-or light smokers with adenocarcinoma." (PMID 24404167, 2014).
infection (19 papers, 2012 to 2025). The state of being infected such as from the introduction of a foreign agent such as serum, vaccine, antigenic substance or organism. "The etiology and pathogenesis of IMT remain uncertain; however, infection, vascular causes, autoimmune disorders and the anaplastic lymphoma kinase (ALK) gene have been proposed." (PMID 24273608, 2013). "We found many variables associated with ANC, including mutational status of EGFR/ALK, concurrent chemotherapy, concurrent infection, high level of troponin or other inflammatory markers, baseline levels or changes in electrolytes, and changes in lab tests associated with kidney or liver function." (PMID 33882890, 2021). "Overall, these findings support therapeutic role for ALK in lethal infection and open a venue for further clinical testing." (PMID 34638546, 2021). "An increased incidence of renal cystic lesions, often with features concerning for malignancy or infection, has been reported in patients with anaplastic lymphoma kinase (ALK) - rearranged advanced non-small cell lung cancer (NSCLC) treated with Crizotinib." (PMID 28209203, 2017). "It has been proposed to be related to infection, trauma, surgery, autoimmunity and chromosomal variation, such as the abnormalities of ALK gene." (PMID 25624905, 2015). "Like mouse ALK, infection of primary hippocampal neurons with a lentivirus carrying constitutively active ALK.Fc, a chimeric protein in which the extracellular domain of human ALK was replaced by the mouse IgG 2b Fc domain for dimerization, dramatically increased accumulation of phosphorylated tau." (PMID 33452442, 2021). "Growth curves were generated after seven or eight days of the second infection demonstrating growth retardation of 70% in SUDHL-1 using CD147 shRNA B or of 59% in SUDHL-1 and 47% in KiJK using CD147 shRNA A, despite the normal expression of ALK, P-STAT3, P-STAT5 and P-STAT1." (PMID 35676454, 2022). "In the present case, while immunohistochemical analyses showed negative staining for ALK, in situ hybridization revealed infection of EBV, which may account for the occurrence of IMT." (PMID 25624905, 2015). "In the case presented neither an infection nor ALK expression could be detected." (PMID 23346443, 2012). "Notably, infection rates did not significantly differ between PKP, EK, or ALK, highlighting the need for consistent infection surveillance." (PMID 40806946, 2025). "The levels of ALT (32.3 ± 11.7 vs. 36.3 ± 12.8, P = 0.002), AST (31.9 ± 12.1 vs. 36.8 ± 13.1, P = 0.001), and ALK (164.2 ± 127.3 vs. 174.4 ± 130.2, P < 0.001) in HCV-positive patients co-infected with HPgV-1 were significantly lower compared to those without HPgV-1 infection." (PMID 40345623, 2025). "The ADVL0912 phase I/II study on 26 children receiving crizotinib for ALK-positive ALCL noted treatment-related grade ≥3 neutropenia (61.5%), lymphopenia, febrile neutropenia, myositis, and skin infection cases (3.8% each; no severe infection in the low-dose group)." (PMID 36291806, 2022).